ZIM3 (zinc finger imprinted 3)
Description:
May be involved in transcriptional regulation.
Synonyms: ZNF657
Tractability: No criterion of Open Targets' tractability assessment is met for any kind of drug.
Gene: Protein-coding gene on chromosome 19 (57,134,096 to 57,145,202, reverse strand). Ensembl gene ENSG00000141946.
Subcellular location: Nucleus
Pathways (Reactome):
Gene expression (Transcription): Generic Transcription Pathway
Gene Ontology:
Molecular function: protein binding; DNA-binding transcription factor activity, RNA polymerase II-specific; RNA polymerase II cis-regulatory region sequence-specific DNA binding; sequence-specific double-stranded DNA binding
Biological process: regulation of transcription by RNA polymerase II; regulation of DNA-templated transcription; regulation of gene expression
Cellular component: nucleus
Genetic constraint (gnomAD): Loss-of-function variants: 10 observed, 12.51 expected, observed/expected ratio (o/e) 0.8, 90% interval 0.49 to 1.35. The upper end of that interval is the gene's LOEUF score, 1.35, which puts it in group 5 of 6, group 1 being the genes least tolerant of losing a copy. Missense variants: 594 observed, 576.85 expected, observed/expected ratio (o/e) 1.03, 90% interval 0.96 to 1.1. Synonymous variants: 204 observed, 209.49 expected, observed/expected ratio (o/e) 0.97, 90% interval 0.87 to 1.09.
Homologues: Orthologues: chimpanzee ZIM3 (99% identical), macaque ZIM3 (90% identical), rabbit ZIM3 (67% identical). Paralogues in human: ZNF300 (45% identical), ZNF658 (43% identical), ZNF33A (43% identical), ZNF461 (43% identical), ZNF182 (43% identical), ZNF630 (42% identical), ZNF30 (42% identical), ZNF568 (42% identical), ZFP14 (42% identical), ZNF267 (42% identical), ZNF717 (42% identical), ZNF782 (42% identical), and 164 more.
Diseases named in the same sentence as ZIM3 in open-access papers:
ZIM3 is named in the same sentence as 7 diseases in open-access papers, as found by Europe PMC text mining. Sharing a sentence is not in itself a finding about the gene and the disease. The quoted sentences say what the papers report.
hepatocellular carcinoma (2 papers, 2022). A malignant tumor that arises from hepatocytes. "Zim3-dCas9 also conferred strong and homogeneous knockdown in HepG2 (hepatocellular carcinoma), HT29 (colorectal adenocarcinoma), and HuTu-80 (duodenal adenocarcinoma) cells without negative impacts on cell proliferation." (PMID 36576240, 2022).
infection (1 paper, 2024). The state of being infected such as from the introduction of a foreign agent such as serum, vaccine, antigenic substance or organism. "This pooled gRNA library was transduced at low multiplicity of infection (MOI) into primary CD4+ T cells previously selected for CBh-ZIM3-dCas9 expression." (PMID 38308274, 2024).
ZIM3 also shares sentences with these, for which no sentence is quoted: acute T-cell leukemia (1 paper); colorectal adenocarcinoma (1); duodenal adenocarcinoma (1); osteosarcoma (1); tumor (1).